HOXA5 (homeobox A5)
Description:
Sequence-specific transcription factor which is part of a developmental regulatory system that provides cells with specific positional identities on the anterior-posterior axis. Also binds to its own promoter. Binds specifically to the motif 5'-CYYNATTA[TG]Y-3'.
Synonyms: HOX1C; HOX1; HOX1.3
Tractability: PROTAC: ubiquitination databases record sites on it.
Gene: Protein-coding gene on chromosome 7 (27,141,052 to 27,143,681, reverse strand). Ensembl gene ENSG00000106004.
Subcellular location: Nucleus
Gene Ontology:
Molecular function: DNA binding; DNA-binding transcription activator activity, RNA polymerase II-specific; DNA-binding transcription factor activity; protein binding; RNA polymerase II cis-regulatory region sequence-specific DNA binding; sequence-specific double-stranded DNA binding; DNA-binding transcription factor activity, RNA polymerase II-specific
Biological process: negative regulation of angiogenesis; negative regulation of erythrocyte differentiation; positive regulation of apoptotic process; positive regulation of gene expression; positive regulation of myeloid cell differentiation; positive regulation of transcription by RNA polymerase II; anterior/posterior pattern specification; regulation of transcription by RNA polymerase II; regulation of DNA-templated transcription
Cellular component: nucleus; chromatin
Genetic constraint (gnomAD): Loss-of-function variants: 12 observed, 19.51 expected, observed/expected ratio (o/e) 0.61, 90% interval 0.39 to 1. The upper end of that interval is the gene's LOEUF score, 1, which puts it in group 4 of 6, group 1 being the genes least tolerant of losing a copy. Missense variants: 352 observed, 382.64 expected, observed/expected ratio (o/e) 0.92, 90% interval 0.84 to 1. Synonymous variants: 159 observed, 156.68 expected, observed/expected ratio (o/e) 1.01, 90% interval 0.89 to 1.16.
Homologues: Orthologues: chimpanzee HOXA5 (99% identical), macaque HOXA5 (99% identical), dog HOXA5 (99% identical), pig HOXA5 (98% identical), guinea pig HOXA5 (98% identical), mouse Hoxa5 (98% identical), rabbit HOXA5 (97% identical), rat LOC103692127 (73% identical), zebrafish hoxa5a (67% identical). Paralogues in human: HOXB5 (60% identical), HOXB4 (36% identical), HOXC4 (35% identical), HOXB6 (34% identical), HOXA4 (34% identical), HOXA7 (34% identical), HOXD4 (34% identical), HOXA6 (33% identical), HOXC5 (32% identical), HOXB7 (32% identical), HOXC6 (30% identical), HOXB8 (30% identical), and 30 more.
Diseases named in the same sentence as HOXA5 in open-access papers:
HOXA5 is named in the same sentence as 130 diseases in open-access papers, as found by Europe PMC text mining. Sharing a sentence is not in itself a finding about the gene and the disease. The quoted sentences say what the papers report.
breast carcinoma (66 papers, 2005 to 2025). "Nearly 70% of all breast carcinomas have decreased HOXA5 expression levels, and its loss correlates with progression to higher-grade lesions." (PMID 37626900, 2023). "Enhanced metastasizing capabilities and an enrichment of breast cancer stem cells were also associated with HOXA5 overexpression." (PMID 34149926, 2021). "Next, the functional role of HOXA5 resulting in aggressive phenotypes in breast cancer cells associated with tamoxifen resistance was assessed." (PMID 34149926, 2021). "Multiple studies reported that HOXA5 was associated with tumor progression, including leukemia, breast cancer, lung cancer, glioblastoma, colorectal cancer, laryngeal squamous cell cancer, and liver cancer." (PMID 34485110, 2021). "In our analysis, we show evidence that high expression levels of HOXA5 is associated with an overall poor survival in ER+ breast cancer patients who have received tamoxifen treatment." (PMID 34149926, 2021). "We utilized the cBioPortal Pathway Mapper to list altered signaling pathways associated with altered levels of HOXA5 in breast cancer." (PMID 34149926, 2021). "Here, we explore any association and function of HOXA5 in breast cancer and investigate its potential mechanism of transcription." (PMID 33384715, 2020). "An independent study reports that HOXA5 expression is repressed in a subset of human breast cancer tissues, and this loss occurs via promoter hypermethylation." (PMID 33384715, 2020). "Here, we investigate if HOXA5 expression is associated with breast cancer and study its transcriptional regulatory mechanism in breast cancer cells." (PMID 33384715, 2020). "HOXA5 overexpression is associated with apoptosis in many cancers, including breast cancer, leukemia, osteosarcoma, lung, and cervical cancer." (PMID 31013831, 2019). "HOXA5 downregulation increased stemness, cell plasticity and aggressiveness of breast cancer, and upregulation induced stemness loss in colon cancer." (PMID 29631562, 2018). "Its re-expression causes apoptotic cell death in breast tumor cells and Hoxa5 is typically silenced in breast cancer." (PMID 29254206, 2017). "In primary breast carcinoma, HOXA5 has also been implicated as a tumor suppressor gene since its expression is lost in >60% breast cancer cell lines and primary tumors." (PMID 22227861, 2012). "Similarly, Hoxa5, upregulated in luminal cells during involution, has been associated with estrogen receptor positive (ER+) breast cancer." (PMID 40925719, 2025). "Computational analyses using RNAinter have confirmed miR-145-5 p’s ability to target Homeobox A5 (HOXA5) (c = 0.1619), a transcription factor implicated in tamoxifen resistance and promotion of mesenchymal-like and stem cell properties in aggressive breast cancer phenotypes." (PMID 40758729, 2025). "Notably, a recent study using a breast cancer model demonstrated that the loss of HOXA5 induced cellular transformation from an epithelial to a basal phenotype." (PMID 37845209, 2023). "HOXA5 expression has also been widely-linked to breast cancer progression." (PMID 35169479, 2022). "Moreover, they located the RARE in the 3’ of the HOXA5 gene, and found that in the MCF10A, ATRA resistant breast cancer cell line, the loss of both RARβ and HOXA5 expression occurred during the neoplastic transformation." (PMID 32012980, 2020).
breast carcinoma (continued). "Moreover, the loss of HOXA5 gene expression in human breast cancer correlates with progression to higher-grade lesions, suggesting that it may act as a tumor suppressor gene." (PMID 29615582, 2016). "In conclusion, this study demonstrates that artesunate has the potential to modulate the malignant progression of breast cancer cells through the lncRNA TUG1/miR-145-5p/HOXA5 axis, offering promising evidence for its anti-cancer effects." (PMID 40758729, 2025). "While HOXA5 acts as a tumor suppressor in breast cancer, lung adenocarcinoma, and cervical cancer, it exhibits oncogenic properties in glioma." (PMID 41209012, 2025). "It suppresses malignancy in nasopharyngeal carcinoma but promotes breast cancer progression by targeting HOXA5." (PMID 41388527, 2025). "In conclusion, artesunate has the potential to modulate the malignant progression of breast cancer cells through the lncRNA TUG1/miR-145-5p/HOXA5 axis, offering promising evidence for its future application in clinical trials for breast cancer treatment." (PMID 40758729, 2025). "This gene set was derived from a study utilizing microarray analysis of an inducible HOXA5 breast cancer cell line (HS578T) to identify genes whose expressions are modified after HOXA5 induction." (PMID 39633428, 2024). "HOXA5 is downregulated in breast cancer, gastric cancer, colorectal cancer, hepatocellular carcinoma, lung cancer, osteosarcoma, and adrenocortical carcinoma but is overexpressed in oral squamous carcinoma, esophageal squamous carcinoma, glioma, and leukemia." (PMID 37834206, 2023). "On the other hand, miR-224-5p was found highly upregulated in both breast cancer cells and tissues, promoting the autophagic and the oncogenic activity of breast cancer cells by targeting HOXA5." (PMID 37298143, 2023). "HOXA5 was discovered to present overexpression in breast cancer and served as a prognostic biomarker for colorectal cancer 7-8." (PMID 35370463, 2022). "HOXA5, a tumor suppressor, is down-regulated in breast cancer, cervical carcinoma, and hepatocellular carcinoma." (PMID 36167790, 2022). "Human umbilical cord mesenchymal stem cells (hUCMSC)-derived exosomal miR-224-5p modulates breast cancer autophagy in cells by involving HOXA5." (PMID 36338993, 2022). "To examine the relationship between RAR and ERK signaling in breast cancer cells, we first verified that expression of potential tumor-suppressive genes, HOXA5 and ELF3, was induced by RA treatment in an RAR-dependent manner in MCF7 breast cancer cells." (PMID 36497371, 2022). "There is literature evidence that the abnormal expression of HOXA family genes including HOXA4 and HOXA5 is closely related to the occurrence and development of diverse human cancers including breast cancer, colorectal cancer and ovarian cancer 7-9." (PMID 35370463, 2022). "HOXA5 is negatively regulated in six sets of lung cancer data, in two of breast cancer, and in the PAH set." (PMID 36101460, 2022). "We also revealed that HOXA5 contributes to breast cancer aggressiveness by modulating the expression of proteins involved in EMT." (PMID 34149926, 2021). "In particular, few studies have reported that HOXA5 is downregulated in breast cancer and that it functions as a tumor suppressor." (PMID 34149926, 2021). "In summary, our data confirmed that HOXA5 plays an important role in the regulation and maintenance of aggressiveness in tamoxifen-resistant breast cancer cells by mediating invasion and migration abilities as well as stem-like characteristics." (PMID 34149926, 2021).
breast carcinoma (continued). "In conclusion, our results delineate a mechanism by which HOXA5 promotes tumorigenesis, cancer progression, and tamoxifen resistance in breast cancer cells." (PMID 34149926, 2021). "Amongst the genes showing differential expression levels between the two cell strains, HOXA5 was one of the genes which showed a dramatic increase in the expression levels in the tamoxifen-resistant breast cancer cells." (PMID 34149926, 2021). "Hoxa5 usually plays tumor promotion roles in severe diseases such as breast cancer, acute myeloid leukemia and colorectal cancer." (PMID 34783294, 2021). "In this study, we demonstrated that HOXA5 is a key molecule in activating the PI3K/AKT signaling pathway in tamoxifen-resistant breast cancer cells." (PMID 34149926, 2021). "Using ChIP assay, we found that HOXA5 expression was significantly overexpressed in tamoxifen-resistant MCF7 (TAMR) breast cancer cells because of reduced H3K27me3 binding." (PMID 34149926, 2021). "Multiple studies reported that high HOXA5 expression was a promotor in tumor progression, including esophageal cancer, breast cancer, gastric cancer, and renal cancer." (PMID 34485110, 2021). "Our studies demonstrate that HOXA5 expression is elevated in breast cancer tissues and in estrogen receptor (ER)-positive breast cancer cells." (PMID 33384715, 2020). "Briefly, the tissue microarray containing the breast cancer tissue and surrounding normal tissue was immunostained using a HOXA5 antibody and analyzed under a microscope." (PMID 33384715, 2020). "Overall, our studies demonstrate that HOXA5 gene expression is regulated by E2, and its expression is upregulated in breast cancers." (PMID 33384715, 2020). "In summary, our studies demonstrate that HOXA5 is overexpressed in breast cancer and is transcriptionally regulated via estradiol in breast cancer cells." (PMID 33384715, 2020). "The same research group had shown that HOXA5 expression is lost in > 60% of breast cancer cell lines and primary tumors." (PMID 32012980, 2020). "In an effort to understand the potential role of HOXA5 in breast cancer, initially we examined HOXA5 expression in various cancer cells and breast cancer tissues." (PMID 33384715, 2020). "As HOXA5 is elevated in ER-positive breast cancer cells and breast cancer tissues, we investigated its gene regulation potential via E2." (PMID 33384715, 2020). "As HOXA5 expression is upregulated in breast cancer, we knocked it down in MCF7 cells and analyzed its impacts on viability." (PMID 33384715, 2020). "As HOXA5 expression is elevated in breast cancer cells and tissues, we investigated its potential regulatory mechanism by E2 in MCF7 cells." (PMID 33384715, 2020). "It has been revealed that HOXA5 protein represses the aggressiveness of colon cancer and breast cancer." (PMID 32736574, 2020). "CBP/p300 and MLL-histone methylases act as ER co-regulators in regulation of HOXA5 expression in breast cancer." (PMID 33384715, 2020). "Here, we investigate potential roles and the gene regulatory mechanism in HOXA5 in breast cancer cells." (PMID 33384715, 2020). "Our studies demonstrate that HOXA5 expression is also augmented in breast cancer tissues in comparison to the corresponding adjacent normal breast tissues." (PMID 33384715, 2020). "We demonstrate that HOXA5 expression is elevated in breast cancer, and its expression is regulated by estradiol (E2)." (PMID 33384715, 2020).
breast carcinoma (continued). "For the tissue expression analysis, a breast cancer tissue microarray (commercial) was analyzed for HOXA5 expression level." (PMID 33384715, 2020). "This suggests the potential presence of multiple modes of action of HOXA5 in different breast cancer subsets." (PMID 33384715, 2020). "Biochemical studies show that estradiol (E2) regulates HOXA5 gene expression in cultured breast cancer cells in vitro." (PMID 33384715, 2020). "Subsequently, they correlated the HOXA5 expression with the ATRA treatment only in RARβ positive breast cancer cell lines." (PMID 32012980, 2020). "Overexpression of HOTAIR and methylation of HOXA5 were also observed in the progression of breast cancer." (PMID 31168296, 2019). "The lowly expressed HOXA5 lead to the functional activation of twist and promoting the development of breast cancer." (PMID 31874629, 2019). "Another RARE located at the 3′ end of the human HOXA5 gene and conserved in the mouse genome was shown to mediate RA responsiveness of HOXA5 in breast cancer cells." (PMID 29615582, 2016). "In breast cancer cell lines and patient tumors, HOXA5 silencing was proposed to result from the methylation of CpG islands in the HOXA5 promoter region." (PMID 29615582, 2016). "Nearly 70% of human breast carcinomas have decreased HOXA5 protein levels compared to normal tissue." (PMID 29615582, 2016). "One recent study showed that the expression of HOXA5 is lost in more than 60% of breast cancer cell lines and primary carcinomas due to promoter hypermethylation." (PMID 25875824, 2015). "In breast cancer cells, high expression of c-myc and subsequent high expression of miR-130a resulted in low HOXA5 expression." (PMID 26219418, 2015). "Since HOXA5 plays a role in apoptosis of breast cancer cells, retinoic acid was reported to regulate HOXA5 through RAR-β." (PMID 25520935, 2014). "Another RARE located at the 3′ end of the human HOXA5 gene was shown to mediate RA responsiveness of the gene in breast cancer cells." (PMID 24705708, 2014). "Its expression is higher in normal breast epithelium than in breast carcinomas, and expression of HOXA5 is lost in over 60% of breast tumors and cell lines, largely due to methylation, while its overexpression has been shown to induce apoptosis." (PMID 16280042, 2005). "Whether HOXA5 promotes breast cancer progression by enhancing glycolysis suggests that, based on molecular docking experiments, Artesunate could inhibit the aggravation of malignant phenotypes through lncRNA TUG1-mediated glycolysis suppression." (PMID 40758729, 2025). "Therefore, this study aims to investigate the potential role of the lncRNA TUG1/miR-145-5p/HOXA5 signaling pathway in mediating the anticancer effects of artesunate in breast cancer." (PMID 40758729, 2025). "We have also shown that the elevated expression of HOXA5 in ER+ breast cancer could result in the acquisition of tamoxifen resistance." (PMID 34149926, 2021). "Furthermore, elevated HOXA5 expression resulted in breast cancer cells acquiring more mesenchymal-like and stem cell traits associated with aggressive breast cancer phenotypes." (PMID 34149926, 2021).